NOBOX (NOBOX oogenesis homeobox)
Description:
Transcription factor which may play a role in oogenesis. Binds preferentially to the DNA sequences 5'-TAATTG-3', 5'-TAGTTG-3' and 5'-TAATTA-3'.
Synonyms: OG2; Og2x; OG-2; POF5; TCAG_12042
Tractability: No criterion of Open Targets' tractability assessment is met for any kind of drug.
Gene: Protein-coding gene on chromosome 7 (144,396,895 to 144,410,227, reverse strand). Ensembl gene ENSG00000106410.
Subcellular location: Nucleus
Pathways (Reactome):
Developmental Biology: M-decay: degradation of maternal mRNAs by maternally stored factors
Gene Ontology:
Molecular function: sequence-specific DNA binding; DNA-binding transcription factor activity, RNA polymerase II-specific; RNA polymerase II cis-regulatory region sequence-specific DNA binding; DNA binding; DNA-binding transcription factor activity
Biological process: regulation of transcription by RNA polymerase II
Cellular component: nucleus; chromatin
Genetic constraint (gnomAD): Loss-of-function variants: 38 observed, 46.92 expected, observed/expected ratio (o/e) 0.81, 90% interval 0.62 to 1.06. The upper end of that interval is the gene's LOEUF score, 1.06, which puts it in group 4 of 6, group 1 being the genes least tolerant of losing a copy. Missense variants: 766 observed, 755.42 expected, observed/expected ratio (o/e) 1.01, 90% interval 0.95 to 1.08. Synonymous variants: 320 observed, 310.3 expected, observed/expected ratio (o/e) 1.03, 90% interval 0.94 to 1.13.
Homologues: Orthologues: chimpanzee NOBOX (98% identical), macaque NOBOX (86% identical), rabbit NOBOX (59% identical), dog NOBOX (53% identical), pig NOBOX (44% identical), mouse Nobox (42% identical), rat Nobox (41% identical), tropical clawed frog hbox10 (19% identical). Paralogues in human: PAX6 (14% identical), PAX7 (12% identical), ARX (11% identical), PAX3 (11% identical), OTP (10% identical), PITX2 (10% identical), UNCX (10% identical), ALX3 (10% identical), RAX (10% identical), PITX1 (9% identical), ALX4 (9% identical), VSX2 (9% identical), and 38 more.
Diseases named in the same sentence as NOBOX in open-access papers:
NOBOX is named in the same sentence as 9 diseases in open-access papers, as found by Europe PMC text mining. Sharing a sentence is not in itself a finding about the gene and the disease. The quoted sentences say what the papers report.
infertile (5 papers, 2011 to 2024). "The importance of this gene is evident as NOBOX knockout mice are infertile, and mutations in the NOBOX gene have been associated with premature ovarian failure (POF), suggesting the essential role of NOBOX in folliculogenesis." (PMID 22321819, 2012). "Mutation of NOBOX was reported in women with POI and infertility." (PMID 35257353, 2022). "NOBOX knockout mice are infertile and lack of NOBOX disrupts expression of many germ-cell specific genes and microRNAs." (PMID 21548929, 2011). "Studies in mouse indicate that NOBOX, SOHLH1/SOHLH2 and LHX8 are co-expressed and cross-regulate each other, either directly or indirectly, thus controlling oocyte development during early follicular progression and therefore their mis-regulation leads to infertility." (PMID 39391877, 2024).
cyst (2 papers, 2010 to 2016). A sac-like closed membranous structure that may be empty or contain fluid or amorphous material. "A number of transcription factors are known to play crucial roles in these processes as well as in germ cell cyst breakdown including Factor in the Germline Alpha (FIGLα) and Newborn Ovary Homeobox Gene (NOBOX)." (PMID 27341508, 2016). "Based on the mouse knockout phenotypes, mutations involving the NOBOX, DMRT4, NR5A1 or StAR genes could be associated with cyst formation, however we did not detect mutations in the coding sequences of these genes in any of the cases described here." (PMID 20593028, 2010).
ovarian disorder (1 paper, 2026). A disease involving the ovary. "Our findings indicate that PAE reduces ovarian reserve through HDAC1-linked epigenetic silencing of Usp9x, exacerbating HIF1α/NOBOX pathway dysfunction, thereby informing aspirin's gestational safety and future interventions for fetal-origin ovarian disorders." (PMID 41524225, 2026).
primary ovarian insufficiency (1 paper, 2024). "Pure heterozygous NOBOX truncation variants induce defective transcriptional activation, leading to primary ovarian insufficiency." (PMID 38523712, 2024). "At the same time, compound heterozygous truncating mutations in NOBOX characterized by double allele deletion mutations cause severe primary premature ovarian insufficiency (POI) with primary amenorrhea in patients in consanguineous marriages." (PMID 38523712, 2024).
cancer (3 papers, 2022 to 2025). A tumor composed of atypical neoplastic, often pleomorphic cells that invade other tissues. "We also identified novel TFs such as NOBOX in HNSC, ZNF280C in KIRP, and POU6F2 in LUSC, which potentially regulate cancer-specific regulatory networks yet remain relatively understudied in those cancer types." (PMID 40748712, 2025). "Two of these markers, NOBOX and PRRX2 show no representation in the literature in association with this cancer type." (PMID 38886487, 2024).
NOBOX also shares sentences with these, for which no sentence is quoted: Obesity (1 paper); Ovarian cyst (1); premature ovarian failure (1); viral disease (1).